BRCA2 (BRCA2 DNA repair associated)
Diseases named in the same sentence as BRCA2 in open-access papers (continued):
Sharing a sentence is not in itself a finding about the gene and the disease.
Fanconi anemia (continued). "Interestingly, however, it has been shown that biallelic, null germline mutations in BRCA2 and PALB2, hypomorphic mutations in BRCA1 and Rad51C, or in the case of RAD51 a dominant mutation, all give rise to a spectrum of clinical symptoms that have features of Fanconi Anaemia (FA)." (PMID 26990772, 2016). "In addition, we confirm variants with pathogenic status in BRCA1 and BRCA2 as they were never encountered in homozygosity except in two cases with resulting Fanconi anemia phenotype (NM_ 000059.3:c.7007G > A:p.Arg2336His and NM_000059.3: c.9152delC, p.Pro3051Hisfs*11)." (PMID 27884173, 2016). "Germline mutations of Brca2 are associated with cancer prone syndromes and Fanconi anemia, and absence of a functional BRCA2 protein induces increased cell sensitivity to DNA crosslinking agents; thus, hAGT activity and degradation might also affect other DNA repair pathways." (PMID 26227971, 2015). "A common DNA damage network between the BRCA and Fanconi anaemia (FA) pathways has been proposed and three FA genes, FANCD1, FANCN, and FANCJ, are identical to the BRCA genes BRCA2, PALB2, and BRIP1." (PMID 24550935, 2014). "The protein product of the Fanconi anaemia gene PALB2 (FANCN) serves as a bridge between BRCA1 and BRCA2." (PMID 23587053, 2013). "A few genetic studies contributed to the identification of pathogenic biallelic variants of BRCA2 in patients with POI in absence of cancer or Fanconi Anemia trait, thus supporting BRCA2 haploinsufficiency as a possible mechanism leading to isolated POI." (PMID 39391877, 2024). "FANCS/BRCA1, FANCD1/BRCA2, FANCN/PALB2 and FANCO/RAD51C are Fanconi anemia (FA) genes." (PMID 37566130, 2023). "The BRCA1/FANCS and BRCA2/FANCD1 gene products have been found to be involved in DNA double strand-break (DSB) repair and DNA interstrand cross-links (ICLs) repair by homologous recombination (HR) and Fanconi anemia pathway." (PMID 31890056, 2019). "BRCA2/FANCD1 and FANCD2/FANCI were found to protect stalled replication forks, indicating that the Fanconi Anemia (FA) pathway may take a role in preventing R loop-dependent genome instability." (PMID 32010626, 2019). "Interestingly, genes from the Fanconi Anemia pathway FANCA, FANCI, FANCD1 (also known as BRCA2) were enriched in radiosensitive GSCs compared to radioresistant GSCs." (PMID 30282933, 2018). "Conversely several components within the Fanconi anemia network, interact with BRCA1 (directly or indirectly) and participate in BRCA1-dependent DNA repair of DSBs, including FANCJ (=BACH1), FANCN (=PALB2), and FANCD1 (BRCA2)." (PMID 23802008, 2013). "Among DNA repair genes, we detected a high presence of members of the Fanconi Anemia Complementation Group (FANCC, FANCD2, FANCG, FANCA, and FANCE), which participate in homologous recombination DNA repair, and genes involved in double-strand break repair (BRCA2, BRIP1, BARD, BLM, CHEK2, and PALB2)." (PMID 30487452, 2018).
Fanconi anemia (continued). "The fact that BRCA2/FANCD1 and BRCA1 directly or indirectly participate in the Fanconi Anemia (FA) pathway, involved in the repair of inter-strand crosslinks (ICLs) that block RF progression suggests that R loops may be an important contributor to genome instability in FA cells." (PMID 26584049, 2015). "Since the detection rate of biallelic pathogenic variants is extremely low, including ataxia telangiectasia for ATM and Fanconi anemia for BRCA1 and BRCA2, we did not describe the autosomal recessive mode of inheritance in the Fact Sheet, except for MUTYH." (PMID 40183848, 2025). "BRCA2 acts as a platform to form multimeric structures–it not only directly binds to RAD51 but also to Partners with Localizer of BRCA2 (PALB2/FANCN) and Fanconi Anemia (FA) Complementation Group D2 (FANCD2)." (PMID 33043007, 2020). "Moreover, BRCA2′s contribution to the repair of cisplatin-induced interstrand crosslinks is more significant than BRCA1, which is likely attributable to the fact that BRCA2, but not BRCA1, functions in the Fanconi anemia repair pathway." (PMID 21779174, 2011).
breast tumors (181 papers, 1995 to 2026). "Comprehensive genomic profiling of the residual breast tumor revealed a BRCA2 reversion mutation (allele frequency: 6.7%) that restored the open reading frame." (PMID 41868534, 2026). "Most BRCA1-mutated breast tumors, and a subset of BRCA2-mutated tumors, present as triple-negative breast cancer (TNBC), which is associated with a poor prognosis and high likelihood of recurrence." (PMID 38956205, 2024). "More rigorous studies are warranted to establish the role of ERα-induced MLH1 in initiation and progression of BRCA2-deficient breast tumors." (PMID 38271119, 2024). "Genetic screening has confirmed that PARG deficiency induced PARPi resistance in mouse breast tumor cells, and even this mechanism was relatively common in BRCA2-deficient mouse breast tumor cell resistance." (PMID 39318358, 2024). "The loss of expression of EZH2 in a murine BRCA2-deficient breast tumour model was associated with acquired PARPi resistance through replication fork stabilization." (PMID 39796639, 2024). "The analyses revealed the presence of the BRCA2 c.9648+1G>A variant in 15% of reads in buccal swab, in 23% of the reads in urine and in 66% of reads in breast tumor, confirming constitutional mosaicism." (PMID 36833429, 2023). "Expression of BRCA2-001/Short was significantly more common in recurrent tumors and further enriched among breast tumors and BRCA1 mutation carriers." (PMID 36344544, 2022). "For radiation-associated secondary malignancies, a significant excess of long-segment-deletions relative to insertions was already described, which can typically be found in BRCA1 or BRCA2 germline-deficient breast tumors." (PMID 34885191, 2021). "Multiple chromosomal abnormalities have been found in breast tumors with the BRCA2 999del5 mutation and in murine cells deficient in the BRCA2 homolog." (PMID 35052422, 2021). "Elevated CDKN1A expression was also detected in BRCA2-mutated breast tumours relative to those carrying wild type BRCA2 gene (TCGA data)." (PMID 34389725, 2021). "Although BRCA2 mutations occur more frequently in ER+ breast tumors, several studies reported BRCA2 mutations in triple-negative breast cancer." (PMID 30038706, 2018). "One BRCA1 and one BRCA2 breast tumor each had somatic pathogenic mutations in the corresponding gene, at 21 and 35% allele frequency, respectively." (PMID 28831036, 2017). "Our computational framework starts by comparing familial breast tumors carrying either BRCA1 or BRCA2 mutations with sporadic cancer samples to generate a BRCAness characteristic profile." (PMID 29146938, 2017). "Absence of locus-specific LOH was found at a particularly high rate for BRCA2 germline mutation-associated breast tumors (46%)." (PMID 28831036, 2017). "First, by applying the RIPSs, we were able to discriminate with fairly high accuracy breast tumors containing germline BRCA1 or BRCA2 mutations from those that occurred sporadically." (PMID 27788678, 2016). "Of note, complete inversions were also significantly enriched amongst BRCA1 and BRCA2 germline-deficient breast tumours (P=2 × 10−16)." (PMID 27615322, 2016). "We found that breast tumors with inherited BRCA1 or BRCA2 mutations tend to have higher RIPSs than sporadic breast tumors." (PMID 27788678, 2016). "Further, breast tumors of male BRCA2 mutation carriers are more likely to present as high-grade, PR-negative, and relatively high rates of HER2-positivity with a micropapillary component to histology have been reported." (PMID 25857409, 2014). "This study has re-estimated the likelihood of BRCA1 or BRCA2 mutation status associated with breast tumor features commonly measured in the clinical setting, by analyzing much larger datasets than previously used for this purpose." (PMID 25857409, 2014). "In another study focusing on BRCA2, 12 tumors out of 89 tumors were found to exhibit a high level of similarity with BRCA2-mutated breast tumors." (PMID 24479546, 2014).
breast tumors (continued). "The breast tumor phenotype of female BRCA2 female mutation carriers is less distinctive than that of BRCA1 mutation carriers." (PMID 25857409, 2014). "The distribution of histopathological features of invasive breast tumors in BRCA1 or BRCA2 germline mutation carriers differs from that of individuals with no known mutation." (PMID 25857409, 2014). "In the current study, we have characterized breast tumors from female carriers of germline mutations in BRCA1 and BRCA2 genes and a cohort of sporadic (unselected) breast tumors by microarray gene-expression analysis." (PMID 23704984, 2013). "To bridge the gap while waiting for NGS to become more widely available we propose to use FISH to screen breast tumors for deletions on 13q and 14q in order to identify tumors potentially associated with BRCA2." (PMID 23284877, 2012). "We have shown that breast tumors arising in patients with germline BRCA2 mutations have a higher frequency of deletions on 13q and 14q than is seen in other breast tumors." (PMID 23284877, 2012). "The loss of pRb observed in the basal/TNP subtype of BRCA2 mutated breast tumors likely reflects acquired defects in the RB1 gene." (PMID 21958427, 2011). "Deletions at 11 q have been described previously in association with BRCA2 breast tumors wherein aberrant expression of ATM has been demonstrated." (PMID 21958427, 2011). "In contrast, the luminal subtypes of BRCA2 mutated breast tumors were associated with high expression of cyclin-D1 gene products (χ2; P = 0.005)." (PMID 21958427, 2011). "Earlier studies from our laboratory have identified BRCA2 -26 wild type GG and mutant AA genotype to provide risk whereas heterozygote GA to provide protection against sporadic breast tumors." (PMID 21092294, 2010). "We used this method to find CNAs that occur more often in BRCA1- or BRCA2-deficient breast tumors compared to BRCA-proficient control tumors." (PMID 20735817, 2010). "The distribution of ER status in breast tumours and CK expression amongst TN tumours from BRCA2 mutation carriers appears to be similar to that in tumours from the population overall." (PMID 20482762, 2010). "Of note, tumors from our mouse models do not give rise to ER-positive luminal tumors, which is the cell type of 70-80% of human sporadic and BRCA2-mutated breast tumors." (PMID 20735817, 2010). "In this work, we report the characterisation of a human breast tumour xenograft obtained from a woman carrying a BRCA2 mutation." (PMID 20877358, 2010). "A remarkable similarity between mouse and human BRCA2-mutated breast tumors was that the peak of both the human (chromosome 20) and mouse (chromosome 2) centered exactly on the Aurora kinase A (AURKA) oncogene." (PMID 20735817, 2010). "Breast tumours arising in carriers of BRCA1 or BRCA2 mutations, however, also differ from one another and from sporadic tumours in terms of their pathological characteristics, including those assessed morphologically or by immunohistochemistry." (PMID 20482762, 2010). "The involvement of the BRCA1 and BRCA2 genes in sporadic breast tumour development has been questioned because somatic mutations in BRCA1 or BRCA2 have not been found." (PMID 19589159, 2009). "We have demonstrated using high-resolution genomic profiling coupled with analysis of tumour phenotypes that the development of a subset of sporadic breast tumours is similar to that of tumours derived from BRCA1- or BRCA2 germline mutation carriers." (PMID 19589159, 2009). "Loss of the wild-type BRCA1 or BRCA2 allele has been shown in breast tumours arising in patients carrying a germline mutation in one of these genes and in some sporadic breast tumours." (PMID 16880780, 2006). "Familial BRCA1 and BRCA2 tumours are associated with young age of onset and are phenotypically distinct from each other as well as from sporadic breast tumours." (PMID 16846527, 2006).
breast tumors (continued). "The strength of the method is exemplified by its application to a published gene expression data set of sporadic and familial breast tumors with BRCA1 or BRCA2 mutations." (PMID 16018805, 2005). "The histopathology of the breast tumours in the BRCA2 exon 3 542G>T mutation carriers is interesting." (PMID 14735197, 2004). "We carried out AI and fluorescence in situ hybridization (FISH) analyses of BRCA2 in breast tumours from germ-line BRCA1 mutation carriers and vice versa." (PMID 11710835, 2001). "Notably, male BRCA2 PVs carriers are significantly more likely to develop cancer, particularly BC, and are at increased risk of developing second breast and non-breast tumors, compared to male BRCA1 PVs carriers." (PMID 38339330, 2024). "Taken together, our findings reveal a role of MLH1 in relieving replicative stress and show how it may contribute to the establishment of BRCA2-deficient breast tumors." (PMID 38271119, 2024). "In addition, a multicomponent analysis of breast tumors in genetically screened PARPi-sensitive and drug-resistant BRCA2 mutated mice determined that depletion of PAR glycohydrolase (PARG) restores PAR formation and partially rescues PARP1 signaling." (PMID 39318358, 2024). "Genetic testing revealed the presence of two distinct BRCA2 gene mutations in the breast tumor." (PMID 37743480, 2023). "Therefore, it is likely to be due to some specific nature of breast tumors in BRCA2 mutation carriers." (PMID 38036573, 2023). "Interestingly, next-generation sequencing (NGS) of the breast tumor revealed an additional BRCA2 mutation." (PMID 37743480, 2023). "Bi-allelic loss of BRCA mutations was seen to be frequent in both germline and somatic mutations, ranging from 81 to 100% for BRCA1 and 92 to 100% for BRCA2 mutations (germline and somatic) for ovarian tumours and 83–96% and 78–80%, respectively in breast tumours." (PMID 34979999, 2022). "Importantly, the MiDAS sites identified in BRCA2-deficient cells also represent hotspots for genomic rearrangements in BRCA2-mutated breast tumors." (PMID 36002001, 2022). "Notably, we found that BRF2 amplification was mutually exclusive to the loss of BRCA1 and BRCA2 in breast tumors, both in the TCGA and METABRIC datasets." (PMID 34359683, 2021). "Furthermore, 9 genes were associated with BRCA1-related breast tumours and 11 genes were associated with BRCA2-related breast tumours." (PMID 33081408, 2020). "Moreover, a study by Bane and colleagues reported that BRCA2-associated breast tumors are characterized by an increased expression of fibroblast growth factor 1 and fibroblast growth factor receptor 2 compared to BRCA1-associated breast tumors." (PMID 31244284, 2019). "Importantly, TNBC accounts for 70% of breast tumors arising in BRCA1 mutation carriers and 16–23% of breast tumors in BRCA2 carriers." (PMID 30909550, 2019). "Although in a minor proportion, our data are in accordance with the results published by the CIMBA group, where the authors reported that 77.0% of women with mutations in BRCA1 had grade III breast tumors, compared to only 50.0% of women with mutations in BRCA2." (PMID 31244284, 2019). "We compared our findings to 319 radiation-naive breast cancers and sarcomas processed by the same sequencing and bioinformatics pipeline: 251 breast tumours; 33 breast tumours with pathogenic BRCA1 or BRCA2 germline mutations; 35 osteosarcomas (see Methods for cohort details)." (PMID 27615322, 2016). "In addition, an apparently sporadic breast tumor was seen in one individual carrying a BRCA2 somatic deleterious mutation." (PMID 25475740, 2014). "In this study, we show that breast tumors from BRCA2 999del5 mutation carriers, displaying luminal- or basal/triple-negative phenotypes (TNPs), differ with respect to patterns of copy-number changes and markers of pRb/p16 pathway dysfunction, suggesting divergent paths of tumor evolution." (PMID 21958427, 2011).